Y_RNA (Y RNA )
Gene: Miscellaneous RNA gene on chromosome 22 (41,648,089 to 41,648,190, reverse strand). Ensembl gene ENSG00000200332.
Homologues: Orthologues: chimpanzee Y_RNA (99% identical), macaque Y_RNA (87% identical), guinea pig Y_RNA (72% identical). Paralogues in human: Y_RNA (91% identical), RNY3 (90% identical), Y_RNA (90% identical), Y_RNA (89% identical), Y_RNA (88% identical), RNY3P1 (87% identical), Y_RNA (87% identical), RNY3P16 (86% identical), RNY3P2 (86% identical), Y_RNA (86% identical), RNY3P3 (85% identical), RNY3P9 (85% identical), and 96 more.